KCNA7 (potassium voltage-gated channel subfamily A member 7)
Description:
Mediates the voltage-dependent potassium ion permeability of excitable membranes. Assuming opened or closed conformations in response to the voltage difference across the membrane, the protein forms a potassium-selective channel through which potassium ions may pass in accordance with their electrochemical gradient (By similarity).
Synonyms: Kv1.7; HAK6
Tractability: Small molecule: an approved drug acts on it; it belongs to a druggable protein family. Antibody: its Gene Ontology location is reachable by antibodies, with high confidence; UniProt predicts a signal peptide or a membrane-spanning region; the Human Protein Atlas places it where antibodies can reach. PROTAC: a small molecule that binds it is known.
Target class: Potassium channels; Ion channel; Voltage-gated ion channel; Voltage-gated potassium channel
Gene: Protein-coding gene on chromosome 19 (49,067,397 to 49,072,699, reverse strand). Ensembl gene ENSG00000104848.
Subcellular location: Membrane
Subcellular location (Human Protein Atlas): Plasma membrane; Vesicles
Pathways (Reactome):
Neuronal System: Voltage gated Potassium channels
Gene Ontology:
Molecular function: protein binding; delayed rectifier potassium channel activity; monoatomic ion channel activity; voltage-gated potassium channel activity
Biological process: action potential; potassium ion transmembrane transport; monoatomic ion transport; potassium ion transport; protein homooligomerization; transmembrane transport
Cellular component: membrane; plasma membrane; voltage-gated potassium channel complex
Genetic constraint (gnomAD): Loss-of-function variants: 17 observed, 20.62 expected, observed/expected ratio (o/e) 0.82, 90% interval 0.56 to 1.24. The upper end of that interval is the gene's LOEUF score, 1.24, which puts it in group 5 of 6, group 1 being the genes least tolerant of losing a copy. Missense variants: 640 observed, 621.34 expected, observed/expected ratio (o/e) 1.03, 90% interval 0.96 to 1.1. Synonymous variants: 298 observed, 269.28 expected, observed/expected ratio (o/e) 1.11, 90% interval 1.01 to 1.22.
Homologues: Orthologues: chimpanzee KCNA7 (99% identical), macaque KCNA7 (98% identical), dog KCNA7 (94% identical), mouse Kcna7 (94% identical), guinea pig KCNA7 (94% identical), rat Kcna7 (94% identical), pig KCNA7 (93% identical), rabbit KCNA7 (65% identical). Paralogues in human: KCNA6 (66% identical), KCNA3 (66% identical), KCNA4 (64% identical), KCNA2 (62% identical), KCNA5 (62% identical), KCNA1 (62% identical), KCNA10 (58% identical), KCNC4 (39% identical), KCNC2 (38% identical), KCNC3 (38% identical), KCNC1 (37% identical), KCND1 (37% identical), and 19 more.
Diseases named in the same sentence as KCNA7 in open-access papers:
KCNA7 is named in the same sentence as 10 diseases in open-access papers, as found by Europe PMC text mining. Sharing a sentence is not in itself a finding about the gene and the disease. The quoted sentences say what the papers report.
gastric adenocarcinoma (1 paper, 2025). "While other potassium voltage-gated genes such as KCNA2, KCNA3, and KCNA5 have been investigated across various cancers—including skin melanoma, uterine corpus endometrial carcinoma, gastric adenocarcinoma, LUAD, and LUSC in-depth studies of KCNA7’s expression in cancer remain lacking." (PMID 40568194, 2025).
lung carcinoma (1 paper, 2025). "Validation at the single-cell level indicated that the FOXI1, FOXB1, and KCNA7 genes were linked to lung cancer progression." (PMID 40568194, 2025). "Notably, we identified for the first time an association between KCNA7 and the occurrence and progression of lung cancer." (PMID 40568194, 2025). "Through further investigation into KCNA7’s functions and regulatory mechanisms, we aim to establish more precise and effective treatment strategies for lung cancer patients." (PMID 40568194, 2025). "Our findings identify an important link to lung cancer development and highlight KCNA7, FOXI1, and FOXB1 as marker genes for CXCL1 cancer subgroups relevant to clinical prognosis." (PMID 40568194, 2025). "Following transcriptomic and single-cell histological analyses, we established that the highly expressed transcription factors FOXI1, FOXB1, and KCNA7 promote lung cancer development and are primarily involved in cellular processes including proliferation, migration, and invasion." (PMID 40568194, 2025). "Collectively, these results suggest that FOXB1 and KCNA7 may serve as biomarkers for prognostic evaluation in lung cancer and provide a novel theoretical foundation for clinical treatment strategies." (PMID 40568194, 2025). "Consequently, we propose that KCNA7 and FOXB1 function as core genes regulating lung cancer recurrence and are associated with poor survival outcomes in NSCLC patients." (PMID 40568194, 2025). "We further explored the effects of KCNA7 and FOXB1 on clinical traits in lung cancer patients." (PMID 40568194, 2025). "The results revealed that the expression levels of KCNA7 and FOXB1 were significantly higher in patients with recurrence lung cancer compared to those in the non-recurrence group." (PMID 40568194, 2025).
cancer (2 papers, 2023 to 2025). A tumor composed of atypical neoplastic, often pleomorphic cells that invade other tissues. "Potassium voltage-gated channel subfamily A member 7 (KCNA7), belonging to a group of potassium channel-associated genes, has garnered increasing attention in cancer research." (PMID 40568194, 2025). "We evaluated the overall genetic alterations in all KCNA genes (KCNA1, KCNA2, KCNA3, KCNA4, KCNA5, KCNA6, KCNA7, KCNA10) using the TCGA Pan-Cancer Atlas dataset, collecting data from 32 human cancers (10,953 patients in total)." (PMID 36978819, 2023). "However, this does not imply that KCNA7 is unrelated to cancer; rather, more specific investigations are needed to explore its expression and role in cancer." (PMID 40568194, 2025).
tumor (1 paper, 2025).
KCNA7 also shares sentences with these, for which no sentence is quoted: diabetes (2 papers); cardiac hypertrophy (1); hypoglycaemia (1); insulin-dependent diabetes mellitus (1); skin melanoma (1); uterine corpus endometrial carcinoma (1).